TUBA3D (tubulin alpha 3d)
Description:
Tubulin is the major constituent of microtubules, a cylinder consisting of laterally associated linear protofilaments composed of alpha- and beta-tubulin heterodimers. Microtubules grow by the addition of GTP-tubulin dimers to the microtubule end, where a stabilizing cap forms. Below the cap, tubulin dimers are in GDP-bound state, owing to GTPase activity of alpha-tubulin.
Synonyms: H2-ALPHA; KTCN9; TUBA2
Tractability: Small molecule: it belongs to a druggable protein family. PROTAC: ubiquitination databases record sites on it.
Gene: Protein-coding gene on chromosome 2 (131,476,119 to 131,482,934, forward strand). Ensembl gene ENSG00000075886.
Subcellular location: Cytoplasm, cytoskeleton
Subcellular location (Human Protein Atlas): Microtubules; Primary cilium
Pathways (Reactome):
Cell Cycle: EML4 and NUDC in mitotic spindle formation; Mitotic Prometaphase; Recruitment of NuMA to mitotic centrosomes; Resolution of Sister Chromatid Cohesion; Sealing of the nuclear envelope (NE) by ESCRT-III; Separation of Sister Chromatids; The role of GTSE1 in G2/M progression after G2 checkpoint
Vesicle-mediated transport: COPI-dependent Golgi-to-ER retrograde traffic; COPI-independent Golgi-to-ER retrograde traffic; COPI-mediated anterograde transport; Gap junction assembly; Microtubule-dependent trafficking of connexons from Golgi to the plasma membrane; Translocation of SLC2A4 (GLUT4) to the plasma membrane
Metabolism of proteins: Carboxyterminal post-translational modifications of tubulin; Formation of tubulin folding intermediates by CCT/TriC; Post-chaperonin tubulin folding pathway; Prefoldin mediated transfer of substrate to CCT/TriC
Signal Transduction: Hedgehog 'off' state; RHO GTPases Activate Formins; RHO GTPases activate IQGAPs
Immune System: MHC class II antigen presentation; PKR-mediated signaling
Neuronal System: Activation of AMPK downstream of NMDARs; Assembly and cell surface presentation of NMDA receptors
Organelle biogenesis and maintenance: Cargo trafficking to the periciliary membrane; Intraflagellar transport
Autophagy: Aggrephagy
Cellular responses to stimuli: HSP90 chaperone cycle for steroid hormone receptors (SHR) in the presence of ligand
Developmental Biology: Recycling pathway of L1
Disease: HCMV Early Events
Hemostasis: Kinesins
Gene Ontology:
Molecular function: GTP binding; GTPase activity; structural constituent of cytoskeleton
Biological process: mitotic cell cycle; cytoskeleton organization; flagellated sperm motility; microtubule-based process
Cellular component: cilium; microtubule cytoskeleton; cytoskeleton; microtubule; sperm flagellum
Genetic constraint (gnomAD): Loss-of-function variants: 24 observed, 34.73 expected, observed/expected ratio (o/e) 0.69, 90% interval 0.5 to 0.97. The upper end of that interval is the gene's LOEUF score, 0.97, which puts it in group 4 of 6, group 1 being the genes least tolerant of losing a copy. Missense variants: 356 observed, 595.99 expected, observed/expected ratio (o/e) 0.6, 90% interval 0.55 to 0.65. Synonymous variants: 185 observed, 232.07 expected, observed/expected ratio (o/e) 0.8, 90% interval 0.71 to 0.9.
Homologues: Orthologues: chimpanzee TUBA3C (100% identical), rat Tuba3a (100% identical), macaque TUBA3E (99% identical), Drosophila melanogaster alphaTub84B (98% identical), Drosophila melanogaster alphaTub84D (97% identical), zebrafish tuba7l (95% identical), tropical clawed frog tuba1cl (64% identical). Paralogues in human: TUBA3C (100% identical), TUBA3E (99% identical), TUBA1A (98% identical), TUBA1B (97% identical), TUBA1C (96% identical), TUBA4A (94% identical), TUBA8 (91% identical), TUBAL3 (72% identical), TUBB4B (42% identical), TUBB4A (42% identical), TUBB (42% identical), TUBB3 (42% identical), and 11 more.
Diseases named in the same sentence as TUBA3D in open-access papers:
TUBA3D is named in the same sentence as 24 diseases in open-access papers, as found by Europe PMC text mining. Sharing a sentence is not in itself a finding about the gene and the disease. The quoted sentences say what the papers report.
cardiac arrhythmia (2 papers, 2018 to 2026). Any disturbances of the normal rhythmic beating of the heart or MYOCARDIAL CONTRACTION. "We also identified five potentially pathologic variants in genes associated with cardiac arrhythmia, including KCNMB1, KCNIP1, DPP6, JUP, F2, and TUBA3D that were identified in SUDEP patients but not present in our living epilepsy cases." (PMID 29619247, 2018).
Astigmatism (1 paper, 2021). A type of refraction error associated with abnormal curvatures on the anterior and/or posterior surface of the cornea. "Some genes (VSX1, TGFBI, and TUBA3D) can also cause degenerative corneal disease, such as TUBA3D in KC disease, a dilatation, thinning, and conical projection of the cornea that can lead to impaired vision, irregular astigmatism, and corneal scarring." (PMID 33532080, 2021).
breast invasive lobular carcinoma (1 paper, 2024). "Specifically, TUBA3D and TUBA3E showed abnormally high expression in breast invasive lobular carcinoma cell lines, whereas the other 3 genes displayed either low or high expression in varying contexts." (PMID 39432642, 2024).
dilated cardiomyopathy (1 paper, 2025). Cardiomyopathy which is characterized by dilation and contractile dysfunction of the left and right ventricles. "Downregulation of TUBA3D and TUBA3E has been identified in dilated cardiomyopathy (DCM,) and may be a significant molecular alteration contributing to the disease." (PMID 41304893, 2025).
parasite (1 paper, 2024). "Expression profiles revealed significant downregulation of mRNA for proteins ENO1, ACTG1, TUBB, and TUBA3D at 3, 6, and 12 h post parasite infection, respectively." (PMID 38504274, 2024).
cancer (2 papers, 2023 to 2024). A tumor composed of atypical neoplastic, often pleomorphic cells that invade other tissues. "While LTF and TUBA3D were identified as significantly downregulated genes, their roles in cancers remain unclear." (PMID 39565059, 2024).
tumor (2 papers, 2022 to 2023). "The remaining mutated genes present in pre-NACT tumor samples from resistant cases, TUBA3D and SLC35G5, were the only two genes retained in the post-NACT tumor samples of resistant cases." (PMID 35501919, 2022). "As mentioned, three genes were mutated exclusively in pre-NACT tumor samples of resistant cases (CSPG4, TUBA3D, SLC35G5)." (PMID 35501919, 2022). "Interestingly, we also discovered three genes (TBC1D12, KERA, and TUBA3D) that have not been previously associated with tumor-related autophagy." (PMID 37628602, 2023). "In this study, we have identified a few commonly mutated genes in pre-NACT tumor samples from either sensitive (DNAH5, CYP2D6, NUTM1) or resistant (CSPG4, TUBA3D, SLC35G5) cases, which suggest that these genes could have a potential utility for prediction of the response to NACT." (PMID 35501919, 2022). "Lastly, three genes (TBC1D12, KERA, and TUBA3D) that contribute to tumor clustering in groups “0” and “1” have not been previously associated with the tumor-related autophagy process." (PMID 37628602, 2023).
TUBA3D also shares sentences with these, for which no sentence is quoted: keratoconus (2 papers); arrhythmogenic right ventricular dysplasia/cardiomyopathy (1); cardiovascular disorder (1); epilepsy (1); fibromuscular dysplasia (1); Holt-Oram syndrome (1); Hyporeflexia (1); idiopathic ventricular fibrillation (1); infection (1); macular degeneration (1); muscular dystrophy (1); Naxos disease (1); paraplegia (1); retinopathy (1); spinal muscular atrophy (1); thyrotoxicosis (1); ventricular septal defect (1).